GPER1 (G protein-coupled estrogen receptor 1)
Diseases named in the same sentence as GPER1 in open-access papers (continued):
Sharing a sentence is not in itself a finding about the gene and the disease.
tumor (continued). "Again, this result confirmed that, during the development of acquired TKIs resistance, GPER1 translocated from nuclei to cytoplasm of tumor cells." (PMID 35664735, 2022). "In conclusion, both ERα and ERβ stimulates urothelial cell proliferation and tumor cells growth, while GPER1 inhibit urothelial cell proliferation." (PMID 36060947, 2022). "The results were also verified in vivo in mice where GPER1 silencing slowed tumor progression which was further potentiated by gefitinib." (PMID 35664735, 2022). "Administering GPER1 agonist G1 reduced the tumor progression and prolonged survival of the treated mice." (PMID 36060947, 2022). "As for GPER1, the present study shows that it exhibits an inhibiting role in tumor growth and migration." (PMID 36060947, 2022). "The ferrocene-linked novel tamoxifen derivatives T5 and T15 can counter the GPER1 induced tumor-promoting effects through direct cytotoxicity due to oxidative stress." (PMID 35337112, 2022). "This study aimed to determine the mechanism of how AR represses GPER1 and thereby by-passes the tumor suppressive action of G-1 treatment in CRPC." (PMID 35018219, 2022). "Activated GPER1 can inhibit the proliferation and growth of tumor cells and improve the efficacy of immunotherapy." (PMID 36060947, 2022). "In vivo study demonstrated that BPAF increased the weight of SK-BR-3 xenograft tumor in nude mice and up-regulated the mRNA levels of most targets related to GPER1-mediated MAPK and PI3K/Akt signaling pathways in SK-BR-3 tumor tissue." (PMID 36497816, 2022). "The addition of gefitinib to the group of knockdown of GPER1 further inhibited tumor growth, with a synergistic inhibitory effect on the tumor growth between inhibition of GPER1and EGFR pathways." (PMID 35664735, 2022). "The G-protein-coupled receptor for estrogen (GPER1) is a transmembrane receptor involved in the progression and development of various neoplasms whose ligand is estradiol (E2)." (PMID 36231664, 2022). "One study using a single cell line, A431, showed that oestrogen receptors ERα and G‐coupled protein receptor (GPR30, or GPER1) modulated expression of tumour markers Cyclin D1 and CD55; however, ERβ downregulated both tumour markers." (PMID 35664979, 2021). "GPER1 was reported to be involved in the regulation of cellular growth, proliferation, and tumor development." (PMID 34631510, 2021). "GPER1 mediated the proliferation of hepatocytes via PI3K and mTOR signaling, and chemical inhibition or knockdown of GPER1 significantly reduced tumor growth in a zebrafish model." (PMID 33425895, 2020). "As expected, exogenous AMF stimulation alone strongly accelerated tumor growth, and this pro-tumor activity was abolished when it was combined with GPER-1 deletion using in vivo tumor burden assay." (PMID 30836961, 2019). "With H&E and immunohistochemical staining, we examined the tumor tissues to further verify that the AMF-induced effect interacted with GPER-1." (PMID 30836961, 2019). "How does presence of GPER-1 influence the behavior of the tumor and its microenvironment in response to therapy?" (PMID 31749762, 2019). "Other agents used in endocrine therapy such as fulvestrant and raloxifene, which antagonize ER-α actions also act as agonists of GPER-1 and can promote tumor progression." (PMID 31749762, 2019). "Our results indicated that stable knockdown of GPER-1 substantially abrogated the tumor growth induced by AMF in EC." (PMID 30836961, 2019). "Another putative estrogen membrane receptor termed G protein-coupled estrogen receptor 1 (GPER), also referred as GPR30, has been proposed to contribute to physiological and tumor promoting effects of estrogens." (PMID 26056044, 2015). "After adjustment for patient age, menopausal status, tumor stage, lymph node status, histological grading, multivariate analysis rendered GPER-1 as an independent, favorable prognostic factor in regard to DFS (HR, 0.569; 95% CI, 0.317-0.991; p = 0.046)." (PMID 23849542, 2013).
tumor (continued). "However, the presence of GPER1 inhibits the full effectiveness of tamoxifen by upregulating several tumor-protective proteins." (PMID 41011284, 2025). "Knowledge of the role and effect of GPER‐1 is still limited, with evidence for both tumor‐promoting and tumor‐suppressing roles, and its importance relative to ER‐α and ER‐β is unknown." (PMID 40634118, 2025). "Moreover, we measured the levels of E2, the primary physiological ligand for GPER1, in the tumor tissues of HCC patients, and the results showed that E2 levels tend to be higher in female patients compared to males." (PMID 39582864, 2024). "Given that GPER1 was suggested to act as tumor suppressor in the ovary, this observation might be explained by the known activation of tumor suppressor genes by H3K4me3 marks." (PMID 39796024, 2024). "Moreover, GPER1 knockdown and cisplatin treatment exerted significant antitumor effects, and the tumor was in a state of growth arrest." (PMID 38383297, 2024). "Interestingly, treatment with E2 caused an increase in GPER1 in HCT116 ASNS+/+ cells, and a decrease in tumor spheroid size was observed." (PMID 38886847, 2024). "GPER1 knockdown slowed tumor growth, resulting in reduced tumor size and weight." (PMID 38383297, 2024). "However, there are also contrary data suggesting tumor-suppressive functions of GPER1 in ovarian malignancies." (PMID 37345182, 2023). "Since GPER1 contributes to a microenvironment that is conducive to tumor development and progression, GPER1 signaling could represent a promising target in anticancer therapy; however, in this regard, the receptor has to be blocked/antagonized." (PMID 36835454, 2023). "Overall, these data suggest that GPER1 might play a potential tumor suppressor role, as demonstrated in other hematological malignancies such as AML, MCL, and WM, and therefore, its activation can trigger anti-tumor effects." (PMID 37759449, 2023). "GPER1 has a tumor-suppressive function in ovarian carcinoma." (PMID 37762008, 2023). "Whether G protein-coupled estrogen receptor 1 (GPER1) is tumor-promoting or tumor-suppressive depends in part on tumor entity." (PMID 37762008, 2023). "As in OC, GPER1 was reported to exert tumor-suppressive as well as oncogenic effects in EC." (PMID 37345182, 2023). "In contrast, several studies suggested a tumor-promoting role of GPER1 in OC." (PMID 37345182, 2023). "For ESCC, GPER1 might function as a tumor suppressor by inhibiting proliferation and promoting apoptosis of the tumor cells." (PMID 37762356, 2023). "In summary, GPER1 can exert tumor-promoting as well as tumor-suppressive effects in OC." (PMID 37345182, 2023). "GPER1 is often involved in the progression of neoplasms with varying impacts." (PMID 37762008, 2023). "Additionally, a high immune-reactive value, which corresponds to elevated GPER1 expression, showed a positive correlation with a high tumor grade." (PMID 37762008, 2023). "However, the activation of GPER1 hinders its anti-tumor capability by raising the intracellular Amphiregulin, IL6, IL8, antiapoptotic proteins, and invasivity promoting factors." (PMID 35337112, 2022). "p38 MAPK inhibitor may block the effects of GPER1, indicating that its tumor-promoting role in ESCC development is mediated by p38 MAPK." (PMID 36060947, 2022). "Tamoxifen is a known agonist of GPER1, a receptor that can promote tumor progression." (PMID 35337112, 2022). "However, GPER1 expression holds back the complete effectivity of tamoxifen, as it increases the expression levels of several tumor protective proteins." (PMID 35337112, 2022). "Moreover, the mRNA expression levels of ESR2 and GPER1 were also significantly lower in PTC tumor specimens than in adjacent normal tissues in female patients." (PMID 35162942, 2022). "In addition to the modulation of the tumor micro-environment, GPER1 activation has a direct immunomodulatory effect on the tumor tissue, per se." (PMID 33133022, 2020).
tumor (continued). "ERα promotes tumor progression, while the role of GPER1 remains controversial." (PMID 33553141, 2020). "Information on the role and impact of GPER1 is still limited, with evidence for both tumor-promoting and tumor-suppressing roles, and its significance relative to ERα and ERβ is unknown." (PMID 32580290, 2020). "Moreover, E2 binding to GPER-1 inhibited in vivo tumor growth and angiogenesis and reduced the expression levels of VEGF, NF-κB/p65, STAT3, and the endothelial marker CD34 in TNBC cell xenograft tumors." (PMID 33114740, 2020). "What's more, GPER1 overexpression could promote cell proliferation and GPER1 knockdown could inhibited tumor growth in vivo." (PMID 33425895, 2020). "Our results indicate that loss of GPER-1 suppresses tumor development and increases survival considerably in the context of AMF-induced EC tumorigenesis and suggest that the AMF-GPER-1 interaction can accelerate tumor progression both in vitro and in vivo." (PMID 30836961, 2019). "The different cell types, tumor microenvironment, and hormonal level may also affect the functions of GPER-1." (PMID 27314054, 2016). "Studies showed that the activation of GPER-1 signaling pathways leads to tumor." (PMID 27314054, 2016). "The GPER1 gene (also known as GPR30) represents an alternative estrogen-responsive receptor, which is highly expressed in tumors where estrogen and progesterone receptors are downregulated and in high-risk tumor patients with lower survival rates." (PMID 20003295, 2009). "Additionally, in the tumor microenvironment, GPER-1 expression has been detected in CAFs." (PMID 39936103, 2025). "In contrast, accumulating evidence suggests that GPER1 might act as a tumor promoter in CRC." (PMID 36384894, 2023). "Thus, it can be inferred that GPER1 activation has a tumor-suppressive effect in this assay." (PMID 37762008, 2023). "Estrogen actions of GPER1 were also shown in both neoplastic transformation of the colon and tumor progression, including colonic motility, immune regulation, and inflammation (referred to in reference 28), further supporting a protumorigenic role of estrogen-activated GPER1." (PMID 36384894, 2023). "The tumor suppressive effects of estrogens were originally thought to be facilitated by estrogen receptors ERα and ERβ, but recent research from our lab has identified a third ER, G-protein Estrogen Receptor 1 (GPER1), that plays a critical role in suppressing PCa growth." (PMID 35018219, 2022). "The present study also observed that BPAF significantly elevated the mRNA levels of GPER1 and the gene expression of some targets associated with PI3K/Akt and MAPK signaling pathways in the hypothalamus, ovary, uterus, liver, and kidney of nude mice with SK-BR-3 xenograft tumor." (PMID 36497816, 2022). "Our study provides evidence that GPER-1 may be a tumor suppressor gene." (PMID 23849542, 2013). "In non-small cell lung cancer, GPER1 can promote the activation of PI3K/AKT/mTOR signaling, induce SCD1 expression, and thereby prevent ferroptosis in tumor cells, facilitating tumor progression." (PMID 41407677, 2025). "GPER1 activation results in the depletion of MYC/c-Myc, inhibition of tumor proliferation, and enhanced immune recognition by tumor cells." (PMID 39684286, 2024). "The pronounced effect of ASNS deletion on suppressing tumor size and volume is promising for the potential targeting of ASNS, and the potential role of E2 and GPER1 mediating this effect is an area of future investigation." (PMID 38886847, 2024). "The IHC staining results indicated that the expression levels of GPER1 and SCD1 in tumor tissues were significantly higher than those in corresponding normal tissues." (PMID 38383297, 2024). "Mechanistically, KRAS MT cells adapt to a reduced nutrient supply by elevating GPER1 and ASNS expression, which in turn supports tumor proliferation." (PMID 39030619, 2024).
tumor (continued). "The findings suggest that the expression of GPER1 and ESR1 RNA in tumor cells is probably regulated by DNA methylation." (PMID 38666956, 2024). "In this study, we analyzed GPER1 expression in primary human macrophages in vitro and in HCC tumor tissues, and found lower levels of GPER1 in proliferating macrophages." (PMID 39582864, 2024). "The effect of GPER1 on the cytotoxicity of cisplatin was measured in vitro using the CCK8 assay and in vivo using xenograft tumor models." (PMID 38383297, 2024). "The membrane estrogen receptor GPER (also known as GPER1 or GPR30) is expressed in colonic epithelia and is the dominant estrogen receptor present once the tumour has developed." (PMID 36293473, 2022). "Only two genes (GPER1 and CYP4F22) were oppositely correlated with SETD7 expression in different subtypes, being enriched in in low-SETD7 tumours for all subtypes except luminal B where they were upregulated in the high-SETD7 group." (PMID 36551516, 2022). "The present study found that BPAF also up-regulated the expression of ERα, GPER1, and EGFR in the hypothalamus, ovary, and uterus of nude mice with SK-BR-3 tumor." (PMID 36497816, 2022). "Despite the low expression of ERα and GPER1 in the NUGC-4 cells, it seemed that estrogen benefited tumor cell survival in normal tumor cells." (PMID 33553141, 2020). "We observed an increased tumor formation ratio in mice injected with AMF, and the silencing of GPER-1 overcame AMF-induced tumor progression." (PMID 30836961, 2019). "In this study, we show that in human EC cells, AMF binds to the membrane receptor GPER-1, induces the transfer of the AMF-GPER-1 complex to the cytoplasm, activates the downstream PI3K pathway, and promotes tumor cell proliferation and apoptosis." (PMID 30836961, 2019). "On the other hand, a decrease in eigenvector centrality indicates that a gene is connected to less influential or weakening genes, possibly resulting in lower relative influence scores or reduced significance in the network, such as ANXA1, GNB3, POMC, GPER1, and TIMP1 in tumor samples." (PMID 40626556, 2025). "While the observed antitumor effects induced by tamoxifen can be attributed to non-estrogen-receptor-dependent mechanisms, the tumor-protective pathways induced by GPER1 interfere with these off-target effects." (PMID 41011284, 2025). "Especially, the significant changes in GPER1 expression in multiple malignancies showed a consistent decrease with no exception, which indicates the role of GPER1 in common tumor inhibition." (PMID 38666956, 2024). "Significant associations were observed between tumor survival and ESR1 methylation (159 records, 68 negative and 91 positive), ESR2 methylation (46 records, 27 negative and 19 positive), and GPER1 methylation (67 records, 35 negative and 32 positive)." (PMID 38666956, 2024). "Through the examination of the relationship between DNA methylation and RNA expression, we discovered a clear correlation between the methylation of CG sites in the promoters of GPER1 and ESR1 and their respective RNA expression in around one-third of tumor types." (PMID 38666956, 2024). "Estradiol activates GPER1 in vitro in the presence of ASNS and suppresses tumor growth." (PMID 38886847, 2024). "Among the 38 tumor types in the database, 14 tumor types consistently exhibited a reduction in GPER1 RNA expression, and there was no one tumor type with significant increase in the case of GPER1." (PMID 38666956, 2024). "The average staining scores of GPER1 protein in the tissue microarray of EAC were significantly higher than normal esophageal samples, and the rate of positive staining increased with the grade of poor tumor differentiation." (PMID 37762356, 2023). "In the tumor tissue, CRY1, TIM, and GPER1 expressions showed circadian rhythms in both the control and the TRF groups, but the circadian rhythm of TIM expression was more robust in the TRF group, while CRY2 were acyclic in the control group and FBXL3 were acyclic in the TRF group." (PMID 37924048, 2023).
tumor (continued). "Thus, our results reveal a novel link between estrogen-activated GPER1 and the induction of key CRC-prone lesions, supporting a pivotal role of the alternate estrogen receptor in colon neoplastic transformation and tumor progression." (PMID 36384894, 2023). "For instance, GPER1 was negatively correlated with immune components in LIHC, MESO and THCA, suggesting its involvement in the immune infiltration of these tumours and the composition of the tumour microenvironment." (PMID 37921845, 2023). "However, the role of AR mediated gene repression in PCa progression and treatment is complex as the AR has been shown to also directly repress tumor suppressor genes such as DEPTOR, E-cadherin, c-Met, and GPER1." (PMID 35018219, 2022). "Gefitinib alone did not inhibit tumor growth, however, knockdown of GPER1 alone delayed tumor growth." (PMID 35664735, 2022). "The observed cytotoxic effects elicited by tamoxifen are explainable by non-estrogen receptor-dependent mechanisms, but the GPER1-induced tumor protective pathways interfere with these off-target effects." (PMID 35337112, 2022). "IHC was performed on the tumor tissue to detect the expression of LHCGR, MC2R and GPER-1." (PMID 32393232, 2020). "GPER1 activation inhibits PD1 production and action of pro-inflammatory cytokines, positioning this receptor as an interesting player for the modulation of the tumor microenvironment." (PMID 33133022, 2020). "Immunohistochemistry (IHC) showed the tumor tissue that stained positive for luteinizing hormone (LH)/human choriogonadotropin (hCG) receptor (LHCGR), whereas negative for both melanocortin 2 receptor (MC2R) and G protein-coupled receptor-1 (GPER-1)." (PMID 32393232, 2020). "With regard to studies suggesting a tumor-suppressive role of GPER-1 in TNBC, one report claimed GPER-1 agonist G-1 to inhibit TNBC cell growth via induction of cell cycle arrest in the G2/M phase, enhanced phosphorylation of histone H3, and caspase-3-mediated apoptosis." (PMID 33114740, 2020). "To further confirm these results, we employed a three-dimensional spheroid culture system to mimic the physiological conditions of tumor growth with AMF stimulation and compared the spheroid-forming ability of the GPER-1 knockdown cells with that of the control cells." (PMID 30836961, 2019). "It was also observed that estrogen activates G protein-coupled estrogen receptor-1 (GPER-1), inhibits the expression VEGF at both protein and mRNA levels, and suppresses the tumor growth and angiogenesis in TNBC xenograft tumor models, in which STAT3 is involved." (PMID 31088482, 2019). "Therefore, examination of the effect of E2 on GPER1 and ASNS could help understand the link between sex sex-related factors that may affect ASNS-expressing tumor cells and attenuated tumor growth in females." (PMID 38886847, 2024). "This also suggests that the effects of GPER1 on tumours may not depend on the amount of expression but rather in the activation." (PMID 37921845, 2023). "G protein-coupled estrogen receptor 1 (GPER-1), a seven transmembrane receptor, could mediate tumor cell proliferation via its rapid non-genomic estrogenic responses in female cancer." (PMID 30836961, 2019). "In a recent study, G-1, which triggered activation of GPER-1, was shown to suppress migration and invasion of TNBC cells by inhibition of epithelial mesenchymal transition (EMT) via NF-κB signals; these results could be confirmed using MDA-MB-231 tumor xenografts in nude mice." (PMID 33114740, 2020). "GPER-1 expression has also been observed in triple-negative breast cancer (TNBC), a neoplasm characterized by a lack of ERα, PR and HER2 receptors." (PMID 39936103, 2025). "Although studies have demonstrated that the rapid non-genomic effects of GPER-1 promote EC progression, interaction of GPER-1 with proliferative factors in the tumor microenvironment has not been clarified." (PMID 30836961, 2019).